CTLA4 (cytotoxic T-lymphocyte associated protein 4)
Diseases named in the same sentence as CTLA4 in open-access papers (continued):
Sharing a sentence is not in itself a finding about the gene and the disease.
tumor (continued). "We conclude that hydrogel-encapsulated anti-CTLA acts as a localized antibody reservoir and that inclusion of hyaluronidase optimizes the blockade of CTLA-4 in TDLN and thereby imparts superior anti-tumor immunity." (PMID 35621582, 2022). "By covalently linking a STAT3 siRNA and a CTLA4-specific aptamer, this conjugate successfully inhibits STAT3 activity, promotes tumor-infiltrating CD8+ T cell functions, and retards tumor growth of PyMT breast cancer under HFD feeding." (PMID 39872079, 2022). "Antibodies are now a mainstay cancer treatment, specifically targeting tumour (e.g. anti‐EGFR and HER2) or immune cells (e.g. anti‐CTLA4, PD‐1 and PD‐L1)." (PMID 35218154, 2022). "For example, genes CTLA4, GITR, and CCR4 are expressed in both Treg populations, but the expression is higher in the tumor-infiltrating Treg population." (PMID 35626725, 2022). "In a mouse model, the combined RT and anti-CD25/CTLA-4 monoclonal antibody decreased Tregs, PD1+CD8+, and PD1+CD4+ T cells, resulting in the suppression of both irradiated and distal unirradiated tumor resulting in improved OS and reduced liver metastasis." (PMID 35155221, 2022). "In the case of TNBC, nanobodies against tumor-specific antigens such as TNF-α, EGFR, CD3, CTLA-4, STAT-3, AKT2 among others, have been generated and tested for targeting cancer cells." (PMID 36507540, 2022). "For individual immune checkpoints in the combined groups (II-VI), there were 22 (39%, PD-L1), 0 (0%, PD-1), 5 (9%, CTLA-4), and 6 (11%, IDO) cases who showed positive IHC staining in the tumor cells." (PMID 36104728, 2022). "Further modification with insertion of ICPI or co-stimulatory ligands (CTLA-4, 4-1BB, CD40-L and OX40-L) was shown to increase therapeutic efficacy in tumour-bearing mice." (PMID 34733287, 2021). "Blockade of PD-1, CTLA-4, and TIM-3 can enhance cetuximab-based cancer immunotherapy to reverse CD8+ tumor-infiltrating lymphocytes dysfunction, thus affecting the prognosis of cancer patients." (PMID 34367282, 2021). "CTLA-4 outcompetes the co-stimulatory molecule CD28 for binding to B7-1/CD80 or B7-2/CD86 expressed on the surface of antigen presenting cells, including tumour infiltrating dendritic cells." (PMID 33995362, 2021). "Anti-CTLA4 re-induces the T-cell activation by antigen presenting cells whereas anti-PD1 inhibits the interaction leading to tumor escape between T-cells and tumor cells in the tumor microenvironment." (PMID 32929554, 2021). "Treatment with ATOR-1015, a bi-specific CTLA-4 antagonist and OX40 agonist antibody, induces T-cell activation and Treg depletion in vitro, reduces tumor growth and improves survival in syngeneic tumor models." (PMID 34966689, 2021). "When exposed to ICI, specifically anti PD1 or anti CTLA4 and anti PD1, the BRCA2mut mammal tumor exhibited a greater response, with significant growth delay, compared to the BRCA2wt cell line." (PMID 34195090, 2021). "Tumor expression of immune checkpoint molecules like PD1, PD-L1 (which binds to PD-1), and CTLA4 (a T-cell immune suppressant that counteracts the stimulatory activity of CD28) are biomarkers of interest to correlate with response to ICI." (PMID 34921236, 2021). "BSJPF also inhibited tumor proliferation by enhancing GLUT1- and LDHA-related glycolysis and the expression of the immune checkpoint molecules PD-L1 and CTLA-4, thereby altering the immune-rejection status of the tumor microenvironment." (PMID 34002799, 2021). "For CD8+ T cells, although the cytotoxic molecules (GZMA, GZMB, NKG7, and PRF1) were highly expressed, a fraction of CD8+ T cells showed positive with exhaustion biomarkers (CTLA4, PDCD‐1, and TIGIT), indicating their tumor‐cytotoxic activity was constrained." (PMID 34185421, 2021). "ICT targets cytotoxic T lymphocyte antigen 4 (CTLA4) and programmed death (ligand) 1 (PD-1/PDL1), used by tumor cells to inhibit anticancer immune responses." (PMID 33466735, 2021).
tumor (continued). "Immune checkpoint inhibitors (ICIs) are monoclonal antibodies that inhibit cytotoxic T lymphocyte antigen 4 (CTLA4) or PD1 and its ligand PDL1 to reactivate the immune system against tumor." (PMID 34675919, 2021). "Tumor cells use inhibitory signaling pathways in the immune system, such as the PD-1/PD-L1, CTLA-4, LAG-3, Tim-3, and CD160 signaling pathways, to inhibit the function of TILs in the TME, resulting in tumor immunosuppression." (PMID 34513820, 2021). "Given that a significant proportion of CD8+ TILs were found to be PD-1+CTLA-4+, a status that is associated with CD8 + T cell exhaustion, we examined the status of CD8+ TILs to find out whether our localized combination therapy could rescue the proliferation of tumor-reactive CD8+ cells." (PMID 34446702, 2021). "Finally, CTLA-4 may be expressed by infiltrating Tregs or exhausted Tcon in tumor lesions." (PMID 33996698, 2021). "The affinity of B7 proteins for CTLA-4 is much higher than for CD28, and for the tumour cell expressing these proteins, the net result is lymphocyte anergy and apoptosis." (PMID 32929195, 2021). "Beyond PD-L1/2 and CTLA4 level, the CYT value reflects the activity of cytotoxic T cells (CTLs) and NK cells due to their powerful ability to lyse tumor cells." (PMID 34796177, 2021). "Previous studies had reported that CTLA4-CD28 chimera gene-modified T cell, which the intracellular signaling domain of CTLA4 was replaced with the CD28 signaling domain, showed significantly enhanced anti-tumor effect in murine tumor models." (PMID 33868277, 2021). "We also discovered that CD38 expression positively correlated with PD-1, CTLA-4, TIGHIT, GITR, LAG-3, and VISTA, indicating that upregulated CD38 levels in tumor microenvironment mediated ICI-resistance." (PMID 34211854, 2021). "Other preclinical studies have shown that blocking CD96 in combination with anti-PD1 or anti-CTLA-4 enhanced NK cell infiltration and IFN-γ production, thereby reducing tumor metastases in the lungs for various types of solid tumors." (PMID 34768814, 2021). "The result demonstrated that PD-L1, PD1, CTLA4, B7-H3 and VSIR all played a role in regulating tumor immunity and were inversely correlated with the score." (PMID 33819918, 2021). "In a Brac1-knockout ID8 tumor model, the combined use of PARP inhibitor veliparib and anti-CTLA-4 resulted in prolonged survival of the mice compared to using veliparib alone." (PMID 34572778, 2021). "We tested the efficacy of HBI-8000 in combination with anti-PD1, anti-PD-L1 or anti-CTLA4 monoclonal antibodies in multiple preclinical tumor models (e.g. MC38, CT26, and A20) to investigate its activity in tumor immunity." (PMID 35070972, 2021). "An anti-tumor memory response was observed in 67% (2/3) of mice previously treated with BEMPEG, anti-CTLA-4, and RT – as determined by the rejection of re-engraftment with LLC." (PMID 33937052, 2021). "Patients treated with anti–PD-1 antibody in monotherapy, a combination of anti-PD-1 and anti-CTLA4 antibodies, or anti-VEGF agents showed better response and longer overall survival if the primary tumor had higher PD-L1 expression and lower A2AR expression." (PMID 33416945, 2021). "In several mouse tumor models, the transdifferentiation of NK cells into intermediate and ILC1-like cells was accompanied by an increase in CTLA-4 expression." (PMID 34885076, 2021). "We generated a cohort of mice that had fully cleared primary tumor either through dual IRE + anti-CTLA-4 therapy, or from resection plus anti-CTLA-4 therapy as a control." (PMID 34162858, 2021). "Tumor ICT, also known as tumor immune checkpoint blockade, becomes a new treatment for cancer since the first antibody targeting CTLA-4 was discovered by Nobel laureate James P. Allison." (PMID 34631531, 2021). "Together with PD-1, CTLA-4 is one of the main targets of ICI, having demonstrated to be pivotal in the reversion on T cell tolerance in tumor microenvironment and in the treatment of autoimmune diseases." (PMID 34359249, 2021).
tumor (continued). "The FLOW results showed that the percentage of CTLA-4+PD-1+ on CD4+ cells (Upper) and FoxoP3+CD25+ on CD4+ immunosuppressive Tregs (Lower) were lower in tumor allografts from combined treatment compared to other single treatments." (PMID 34093869, 2021). "To verify our guess, we investigated tumor-related immune checkpoints, including CD273, CD274, CTLA-4, and the ones that were newly emerging, LAG-3, TIM-3, TIGIT, CD276, BTLA, and IDO1, between the two subgroups." (PMID 33558879, 2021). "Abs to CTLA-4 block the inhibition of CD80/CD86-dependent T cell activation and in turn prolong anti-tumor activity." (PMID 34205484, 2021). "PD-L1 positivity has been reported from 19% to 64%; herein, the IM tumor samples showed 20% PD-L1 positivity, 30% intT CTLA-4, and 9% strml CTLA-4 expression, which are in agreement with previous reports." (PMID 34944876, 2021). "Future immunoprofiling of the tumor microenvironment of UPS patients treated with anti-PD1 and anti-CTLA-4 therapies are needed to provide clinical insight into these biological observations." (PMID 33864502, 2021). "As the efficacy of immune checkpoint blockade is dependent on tumor-infiltrating immune cells and tumor-specific T cell responses, increased infiltration of TC-1/dCD80-1-induced tumors by immune cells might contribute to the sensitivity of these tumors to anti-CTLA-4 therapy." (PMID 33923750, 2021). "Furthermore, the impact of a combination of anti-CTLA-4 antibodies and therapeutic cancer vaccines has been identified as a promising combination therapy, altering the balance of regulatory T cells by increasing effector T cells in tumors with enhanced anti-tumor function." (PMID 34960142, 2021). "Durable tumor growth was achieved with combined BEMPEG and anti‐CTLA‐4 or anti‐PD‐1 checkpoint inhibition." (PMID 33152115, 2021). "Tumor growth was significantly reduced in mice treated with RT, BEMPEG, and anti-CTLA-4 over dual therapy combinations or monotherapies (p<0.001)." (PMID 33937052, 2021). "The IDO has been suggested as a mechanism of tumor resistance and, in another study, it was demonstrated that IDO can compromise the activity of anti–CTLA-4, anti-PD-1 and anti-PD-L1." (PMID 34829916, 2021). "The most conventional way for ICB is to block the cytotoxic T lymphocyte antigen-4 (CTLA-4) and programmed death receptor-1/programmed death ligand-1 (PD-1/PDL-1) pathways, which can reactivate tumor-suppressed immune cells." (PMID 34842684, 2021). "Similarly, cyclophosphamide administered 1 day before could enhance the antitumor effect of anti-CTLA4 antibody, whereas, treatment with the reversed-sequence regimen led to the apoptosis of proliferating tumor-specific CD8+ T cells and then attenuated tumor control." (PMID 33541368, 2021). "For example, the high expression of PD-L1 in tumor tissue inhibits the function of tumor infiltrating CD8 + T cells, and the CTLA-4 will exert its inhibitory functions on the initial T cells activation, leading to tumor immune escape." (PMID 34349038, 2021). "Studies have found that exosomes derived from tumors carry immunosuppressive proteins, including PD-1, CTLA-4, FasL, TRAIL, CD39, and CD73, which induce apoptosis and depletion of T lymphocytes to achieve tumor immune escape." (PMID 34744733, 2021). "These reinvigorated CD8 + T cells are, at least to some extent, tumor-antigen specific and their expansion in the TME under anti-CTLA-4 correlates with response in a number of human studies." (PMID 33602280, 2021). "STAT3 activation in B-cells enhances tumor angiogenesis via upregulation of VEGF in lung cancer allografts and increases surface expression of immune checkpoint molecules such as CTLA4." (PMID 34944848, 2021). "EBV-positive gastric cancers reveal a higher expression of immune checkpoint genes (e.g., PD-1, CTLA-4) and higher histological lymphocytic infiltration compared with MSS(microsatellite-stable) tumours." (PMID 33673374, 2021).
tumor (continued). "Immune checkpoint molecules, such as CTLA4, NRP1, TNFSF15, CD44, and BTLA, are present in the TME or on the surface of tumor cells, and they negatively regulate T cell activation." (PMID 34926701, 2021). "DUSP12 expression was positively correlated with the abundance of tumor-infiltrating CD4+ T cells, macrophages, neutrophils, dendritic cells, and expression of the immune-checkpoint moieties HARVC2, TIGIT, CTLA4 and PDCD1." (PMID 34414037, 2021). "In both models, the combination of SLC-0111 and anti-PD1/anti-CTLA4 agents reduced the number of T regulatory cells (Tregs) and T-helper 17 cells (Th17), increased the number of Th1, CD8+ cells in tumor tissue and granzymes production by B-cells." (PMID 34948200, 2021). "Immune checkpoint blockade (ICB) agents, such as those targeting CTLA-4 or programmed death (PD)-1, are designed to improve the ability of CD8+ T lymphocytes to maintain effector function and kill tumor targets." (PMID 34064933, 2021). "Further, the density of CTLA-4+ TILs in ICC tissues is related to aggressive clinicopathologic features, such as preoperative serum CA19-9, larger tumor size, lymph node metastasis, and high TNM stage." (PMID 34526987, 2021). "In murine tumor models with high PD1+ T cells, CD40 agonism reversed T cell exhaustion and enhanced response to anti-PD-1 and anti-CTLA-4 immune checkpoint inhibition, suggesting a re-sensitization benefit for patients who experience resistance to ICI." (PMID 33572196, 2021). "The best overall response rate and progression-free survival (PFS) were analyzed depending on the expression of CD68, CD163, PD-1, LAG-3, TIM-3, CTLA-4, TIGIT, CD163/c-maf in the tumor microenvironment in primary and sequential biopsies." (PMID 34830831, 2021). "Synergy between evofosfamide and ICI has been observed in other tumour models, including HNSCC, where combination evofosfamide and anti-CTLA-4 significantly improved survival compared to anti-CTLA-4 alone." (PMID 33923305, 2021). "The combination of primary tumor RT or resection and BEMPEG and anti-CTLA-4 reduced spontaneous metastasis and improved survival without any noted toxicity." (PMID 33937052, 2021). "With regard to anti-CTLA-4, it appears reasonable that it should be given before LTD in order to start the proliferation of T cells in preparation for the response of tumor-specific T cells that will be induced by the LTD." (PMID 34307177, 2021). "High expression of immunosuppressive molecules such as PD-L1, CTLA4, TIM-3, and IDO by cells in the tumor cell microenvironment is one of the mechanisms of immune escape from tumor cells." (PMID 34198652, 2021). "We also observed increased expression of B7-H3, Bcl-2, CTLA4, LAG3, Tim-3, PD1, PDL1 and STING in the second sample compared with the first sample (and some differences appear contingent upon the tumor or stroma compartment)." (PMID 34838031, 2021). "Univariate survival analysis revealed that positive VDR tumor expression (P-value = 0.001) and high VDR tumor expression (p-value = 0.001) have a good prognostic impact on the outcome of patients, but CTLA4 and other variables weren’t significant." (PMID 33906311, 2021). "CTLA-4 binds to its ligands CD80 (B7-1) and CD86 (B7-2) and inhibits T-cell activation, negatively regulates T-cell functions, and mediates tumor immunosuppression." (PMID 34943817, 2021). "We then assessed functional profiles of tumor-infiltrated CD4+ and CD8+ T-cells and their expression of immune checkpoint molecules (PD-1 and CTLA-4)." (PMID 33391535, 2021). "These cSCC CD69+/CD103+ TRMs exhibited increased IL-10 production, and higher CD39, CTLA-4 and PD-1 expression compared with CD103− TRMs in the tumor." (PMID 33479027, 2021). "Primary tumor destruction by irreversible electroporation (IRE), followed by anti-CTLA-4 immune checkpoint inhibitor (ICI), promotes robust expansion of tumor-specific CD8+ T cells in blood, tumor, and NLTs." (PMID 34162858, 2021).
tumor (continued). "The expression of immune checkpoints, such as PD-1, CTLA-4, TIM-3 and V-domain Ig suppressor of T-cell activation (VISTA) in immune cells can mediate tumor immune resistance." (PMID 34829916, 2021). "A recent elegant model took advantage of tumor-bearing Foxp3-DTR mice to deplete these cells in anti-PD-1 and anti-CTLA-4 treated mice." (PMID 33571254, 2021). "Ourfindings demonstrated that in response to CTLA-4 specific nanobody stimulation, DC-CIK cells exhibited a better anti-tumor effect." (PMID 34525966, 2021). "The first was CTLA4, which binds CD80/CD86 to negatively regulate T-cell activation and blockade leads to anti-tumor immune responses." (PMID 34394102, 2021). "Anti-CTLA-4 mAb, an approved ICI, activates effector T cells by blocking the inhibitory signaling axis and depleting Tregs at the tumor site through antibody-dependent cellular phagocytosis or antibody-dependent cellular cytotoxicity." (PMID 33801815, 2021). "Indeed, in melanoma patients treated with anti-CTLA4 antibody, NSCLC patients receiving anti-PD1 antibodies and urothelial carcinoma patients receiving anti-PD-L1 therapy, the extent of DNA damage (that corresponds to tumor mutational burden and neoantigen load) correlates with therapeutic response." (PMID 34012451, 2021). "We chose to use a dual checkpoint blockade regimen given our observation that 90Y-NM600 treatment increased CTLA-4 expression on CD4+ T cells and PD-L1 expression on tumor cells." (PMID 33995649, 2021). "CTLA-4 was hyperactivated in tumor samples from patients with ICC, and the high density of CTLA-4+ TILs (TILsCTLA-4 High) was significantly correlated with malignant characteristics." (PMID 34526987, 2021). "Immune checkpoint blockade, including inhibition of the programmed death 1 (PD-1) receptor pathway or CTLA4/CD152, aims to reinvigorate the host anti-tumor immune response." (PMID 33403469, 2021). "Regulatory T cells can act negatively in the tumor, by blocking T helper cell and CTL functions through CTLA-4." (PMID 34960142, 2021). "Anti-CTLA-4 ICB, for instance, supports the induction phase of anti-tumor T cell responses, while ICB that targets the PD-1/PD-L1 axis serves mainly to maintain the effector phase of anti-tumor T cell responses." (PMID 34073258, 2021). "Analysis of the tumor EV-educated macrophages (TEMs) showed secretion of a variety of factors including CXCL1, CTLA-4, IFNG, OPN, HGF, TGFB, and CCL19 capable of remodeling the surrounding tumor stroma and immune infiltrate." (PMID 34298673, 2021). "have demonstrated that anti-PD-1/anti-CTLA-4 therapy can upregulate VISTA expression, leading to immune-resistance development and tumor relapse." (PMID 34093577, 2021). "After tumor-infiltrating lymphocytes were extracted, we analyzed PD-1 and CTLA4 expression on CD8+ T cells and Foxp3 expression in CD4+ T cells and CTLA4 expression on CD4+ T cells in the control, PTX, and PTX+US+MB groups." (PMID 34271256, 2021). "Anti-CTLA-4 was injected once every 3 days for four total doses, beginning the day following IRE treatment, and tumor outgrowth was monitored." (PMID 34162858, 2021). "Treg cells has the ability to limit the function of antigen presenting cells by CTLA-4 dependent downregulation of CD80 and CD86 expressions, thereby evading tumor antigen presentation and tumor-specific T cell activation." (PMID 34012451, 2021). "A recent prospective single arm clinical study evaluating RT and anti-CTLA-4 in patients with NSCLC demonstrated safety and in favorably responding patients showed that RT-induced T cell recognition of tumor-specific neo-antigens." (PMID 33937052, 2021). "For instance, scRNA-seq identified a subset of tumor-initiating stem cells in squamous cell carcinoma, which selectively express CD80 molecule and bind to the CTLA4 on cytotoxic T cells and thus damage the activity of T cells." (PMID 34722635, 2021).